MUC4 (mucin 4, cell surface associated)
Description:
Membrane-bound mucin, a family of highly glycosylated proteins that constitute the major component of the mucus, the slimy and viscous secretion covering epithelial surfaces. These glycoproteins play important roles in the protection of the epithelium and are implicated in epithelial renewal and differentiation. Regulates cellular behavior through both anti-adhesive effects on cell-cell and cell-extracellular matrix interactions and its ability to act as an intramembrane ligand for ERBB2. Plays an important role in proliferation and differentiation of epithelial cells by inducing specific phosphorylation of ERBB2. In polarized epithelial cells, segregates ERBB2 and other ERBB receptors and prevents ERBB2 from acting as a coreceptor. The interaction with ERBB2 leads to enhanced expression of CDKN1B. The formation of a MUC4-ERBB2-ERBB3-NRG1 complex leads to down-regulation of CDKN1B, resulting in repression of apoptosis and stimulation of proliferation. Its ability to promote tumor growth may be mainly due to repression of apoptosis as opposed to proliferation.
Synonyms: MUC-4; ASGP; HSA276359
Tractability: Antibody: UniProt places it where antibodies can reach, with high confidence; its Gene Ontology location is reachable by antibodies, with high confidence; UniProt predicts a signal peptide or a membrane-spanning region.
Gene: Protein-coding gene on chromosome 3 (195,746,765 to 195,811,973, reverse strand). Ensembl gene ENSG00000145113.
Subcellular location: Cell membrane (Mucin-4 beta chain); Cell membrane (Mucin-4 alpha chain); Secreted; Cell membrane (Isoform 3); Secreted (Isoform 11); Secreted (Isoform 15); Cell membrane (Isoform 17)
Pathways (Reactome):
Disease: Defective C1GALT1C1 causes TNPS; Defective GALNT12 causes CRCS1; Defective GALNT3 causes HFTC
Metabolism of proteins: O-linked glycosylation of mucins; Termination of O-glycan biosynthesis
Immune System: Dectin-2 family
Gene Ontology:
Molecular function: ErbB-2 class receptor binding; extracellular matrix constituent, lubricant activity
Biological process: maintenance of gastrointestinal epithelium; cell-matrix adhesion
Cellular component: extracellular exosome; extracellular region; vesicle; extracellular matrix; Golgi lumen; membrane; plasma membrane
Genetic constraint (gnomAD): Loss-of-function variants: 200 observed, 236.01 expected, observed/expected ratio (o/e) 0.85, 90% interval 0.75 to 0.95. The synonymous counts are far from expectation, so gnomAD's model fits this gene poorly and the ratio says little. Missense variants: 5,591 observed, 4,397.2 expected, observed/expected ratio (o/e) 1.27, 90% interval 1.24 to 1.3. Synonymous variants: 2,203 observed, 1,812.3 expected, observed/expected ratio (o/e) 1.22, 90% interval 1.17 to 1.26.
Homologues: Orthologues: chimpanzee MUC4 (19% identical), macaque MUC4 (19% identical), mouse Muc4 (17% identical), dog MUC4 (15% identical), Drosophila melanogaster mesh (3% identical), Caenorhabditis elegans dec-7 (3% identical), zebrafish si:ch73-105b23.6 (3% identical), Caenorhabditis elegans F54D1.6 (2% identical), Caenorhabditis elegans R09E10.5 (2% identical). Paralogues in human: SUSD2 (3% identical), RTL9 (2% identical).
Diseases named in the same sentence as MUC4 in open-access papers:
MUC4 is named in the same sentence as 229 diseases in open-access papers, as found by Europe PMC text mining. Sharing a sentence is not in itself a finding about the gene and the disease. The quoted sentences say what the papers report.
pancreatic cancer (162 papers, 2004 to 2025). "Mucin-4 (MUC-4) is a membrane glycoprotein which is associated with pancreatic cancer and metastasis, and it has been targeted as a promising vaccine candidate." (PMID 38776309, 2024). "In the context of ICI-therapy MUC4 has been proposed as a novel tumor-associated antigen in pancreatic cancer, while in colorectal cancer, MUC4-mutation was found to be associated with high TMB and increased T-cell infiltration." (PMID 39238637, 2024). "While the genetics the Pan02 cells remain to be fully elucidated, Pan02 (also known as Panc02) cells are reported to carry many common mutations in human pancreatic cancers, including Muc1 and Muc4." (PMID 38547077, 2024). "MUC4/Y, one of the MUC4 transcript variants, was reported to be overexpressed in pancreatic cancer, in which it upregulated NOTCH3 expression, promoting tumor angiogenesis and metastasis." (PMID 37853162, 2023). "MUC4 has been identified as a potential marker for the diagnosis of pancreatic cancer and is associated with a poor prognosis." (PMID 37324940, 2023). "Graviola not only reduces MUC4 expression but also causes a metabolic catastrophe and cytotoxicity, thus reducing migration and invasion of pancreatic cancer cells." (PMID 36139697, 2022). "Mutations in Muc4 have been found in various types of cancers, and studies on colon cancer and pancreatic cancer have reflected that Muc4 mutation is associated with tumor immunity." (PMID 36430789, 2022). "MUC4 is a high-molecular-weight glycoprotein that is irregularly overexpressed in pancreatic cancer cells, and its downregulation is associated with reduced motility and migration of tumor cells." (PMID 35236304, 2022). "Recent studies suggest that MUC4 has been implicated in pancreatic cancer pathogenesis and is expressed in various normal and cancer tissues." (PMID 34336844, 2021). "MUC4 is associated with pancreatic cancer and was proposed as a marker to differentiate pancreatic cancer from pancreatitis." (PMID 34071263, 2021). "In pancreatic cancer cells, increased gene expression for mucin 4 (MUC4—cell surface associated, mucin 4) is observed." (PMID 34680441, 2021). "Generally, B4GALT5 is a membrane-bound glycoprotein, and it was linked with pancreatic cancer through MUC4." (PMID 34071263, 2021). "The methylation status of GRAP2, ICAM3, A2ML1, MUC1, and MUC4 can influence the expression of these genes, which is associated with survival of pancreatic cancer." (PMID 33302876, 2020). "It has also been reported that TQ inhibits MUC4 expression, a primary oncogene associated with cell proliferation and progression of pancreatic cancer cells." (PMID 31141941, 2019). "Mucin 4 (MUC4) is a mucin protein encoded by the MUC4 gene and identified in the majority of pancreatic cancers." (PMID 34164227, 2018). "The transmembrane glycoprotein mucin 4 (MUC4) is aberrantly expressed in pancreatic cancer and associated with increased invasiveness and inversely correlated with prognosis." (PMID 29144412, 2017). "Our previous studies first reported that its splice variant, MUC4/Y can be a model of MUC4 (MUC4 gene fragment is more than 30KB, too huge to clone and eukaryotic express) in pancreatic cancer." (PMID 28060749, 2017). "MUC4 is a high molecular weight membrane protein that is overexpressed in pancreatic cancer (PC) and is associated with the development and progression of this disease." (PMID 27287498, 2016). "Pancreatic cancer has been the favored model to decipher the cellular mechanisms and the intracellular signaling pathways associated with MUC4 altered expression." (PMID 26682251, 2015). "Smoking is a well-known risk factor for pancreatic cancer, while MUC4 is aberrantly over expressed in pancreatic cancer and contributes to its pathogenesis." (PMID 22537161, 2012).
pancreatic cancer (continued). "Growing evidence suggests that the MUC4 mucin, due to its overexpression in several malignancies, is a potential marker for diagnosis, particularly for the lethal pancreatic cancer where its association with the early neoplastic lesions has been established." (PMID 21886786, 2011). "MUC4 causes increased phosphorylation of Bad in response to gemcitabine treatment of pancreatic cancer cells, and thereby facilitates increased binding with 14-3-3 proteins." (PMID 19738614, 2009). "Altogether, these data establish a strong association between MUC4 expression and pancreatic cancer pathogenesis." (PMID 17595659, 2007). "A direct association of MUC4 overexpression has been established with the degree of invasiveness and poor prognosis of pancreatic cancer." (PMID 17595659, 2007). "Our in vivo studies also indicated that mini-MUC4 expression is associated with increased tumorigenicity of human pancreatic cancer cells." (PMID 17595659, 2007). "By enzymatically removing most of the N-linked glycans from membrane glycoproteins in BxPC3 pancreatic cancer cells, the increased MUC-4 antigen exposure resulted in ~25x faster association, ~37x higher affinity, and two distinct well-resolved interaction modes." (PMID 38776309, 2024). "Enzymatic N-linked deglycosylation of pancreatic cancer cells allowed testing of the hypothesis that aberrant N-linked glycosylation surrounding MUC-4 plays a major role in hindering its binding interactions." (PMID 38776309, 2024). "Interestingly, a study found that MUC4 expression in pancreatic cancers is associated with enhanced sensitivity to bortezomib." (PMID 34651428, 2021). "Furthermore, MUC4, encoding a large transmembrane mucin, is often overexpressed in various epithelial malignancies, such as pancreatic cancer, prostate cancer, lung cancer, and breast cancer, and is thought to play an important role in tumor cell biology." (PMID 34457026, 2021). "MUC4 can be explored in pancreatic cancer as an early diagnostic tool." (PMID 34336844, 2021). "Though previous reports have suggested that MUC1, MUC4, and DNA-PKcs might enhance pancreatic cancer chemoresistance, the underlying mechanism remains largely unknown." (PMID 32123287, 2020). "We showed that MUC4 expression is associated with a poorer overall survival in TCGA cancers with different localizations including pancreatic cancer, bladder cancer, colon cancer, lung adenocarcinoma, lung squamous adenocarcinoma, skin cancer and stomach cancer." (PMID 30236127, 2018). "Therefore, MUC4 expression is associated with a poorer overall survival in different cancers including pancreatic cancer." (PMID 30236127, 2018). "We had also previously showed that the human mucin MUC4 forms a complex at the membrane with the oncogenic receptor ErbB2 and that loss of MUC4 in pancreatic cancer cells led to an increased sensitivity to gemcitabine and an increased expression of hCNT1 correlated to cell survival." (PMID 25890497, 2015). "In this study, we have demonstrated increased expression of HER3 in HER2 knockdown cells, which may associate with MUC4 for pancreatic cancer cell proliferation." (PMID 26035354, 2015). "In addition, MUC4 is also overexpressed in breast, gastric and ovarian cancer, and its overexpression has been associated with the poor prognosis of pancreatic cancer and cholangiocarcinoma." (PMID 25261375, 2014). "Furthermore our studies have established that MUC4 is associated with drug resistance in pancreatic cancer." (PMID 23408941, 2013). "However, the molecular mechanisms underlying the dysregulation of MUC4 observed in pancreatic cancer are still poorly understood." (PMID 22537161, 2012). "As the MUC4 overexpression is associated with an increased motility of pancreatic cancer cells, we examined whether the MUC4 overexpression in gastric cancer is associated with an increase in cell motility or not." (PMID 18781152, 2008).
pancreatic cancer (continued). "For example, R848@M2pep-MPsAg derived from RAW264.7 cells stably overexpressing the lung cancer-associated antigen melanoma-associated antigen (MAGE) A3 or pancreatic cancer-associated antigen MUCIN-4 (MUC4) might be used to treat lung cancer or pancreatic tumors, respectively." (PMID 37704614, 2023). "Increased MUC4 expression was significantly correlated with prolonged survival time in breast cancer, colorectal cancer, and kidney renal cell carcinoma, while it was associated with poor survival in ovarian cancer, brain cancer, lung cancer, pancreatic cancer, thymoma, bladder carcinoma." (PMID 34336844, 2021). "In the present study, we used MUC4 antibodies (anti-MUC4) labeled with IRDye800CW to brightly target human pancreatic cancer liver metastases and peritoneal carcinomatosis in nude mouse models." (PMID 40563681, 2025). "MUC4 antibodies conjugated with a fluorescent dye were effective in labeling primary pancreatic cancer in orthotopic nude mouse models." (PMID 40563681, 2025). "In summary, modulation of MUC4 expression via the IFN-γ/JAK/STAT1 pathway significantly promotes pancreatic cancer cell proliferation and metastasis." (PMID 40909948, 2025). "MUC4 expression is involved in the neoplastic transformation and progression of pancreatic cancer; it influences the interactions and communications between the tumor microenvironment and cancer cells." (PMID 40563681, 2025). "Galectin-3 (Gal-3), an endogenous lectin, helps stabilize MUC4 mRNA in the cytoplasm, which is highly expressed in pancreatic cancer cells." (PMID 40699805, 2025). "Under pathological conditions, particularly in pancreatic cancer, MUC4 is markedly overexpressed and contributes to tumorigenesis by facilitating the adhesion of tumor cells to endothelial cells and promoting metastasis." (PMID 40909948, 2025). "In the study of pancreatic cancer, the inhibition of MUC4 expression resulted in reduced tumor metastasis by enhancing cell proliferation and reducing apoptosis." (PMID 40699805, 2025). "Previously, we used MUC4 antibodies labeled with IRDye800CW (anti-MUC4-IR800) to target primary human pancreatic cancer in orthotopic cell line mouse models." (PMID 40563681, 2025). "Research has elucidated the regulatory role of the IFN-γ/JAK/STAT1 pathway in modulating MUC4 expression within pancreatic cancer cells." (PMID 40909948, 2025). "The present study shows that fluorescent MUC4 antibodies brightly label metastatic pancreatic cancer in nude mouse models." (PMID 40563681, 2025). "The results demonstrated the ability of anti-MUC4-IRDye800CW to target and brightly label metastatic tumors in two human pancreatic cancer cell line mouse models." (PMID 40563681, 2025). "MUC4 is a marker for pancreatic cancer and is highly immunogenic, and vaccines have been developed to target cells expressing MUC4." (PMID 41011627, 2025). "MUC1 is overexpressed in pancreatic, lung, breast, colon, and ovarian cancers, while MUC4 overexpression has been observed in colon adenocarcinoma and pancreatic cancer." (PMID 39767713, 2024). "This present study demonstrated that anti-MUC4 antibodies conjugated to near-infrared dyes offer precise in vivo labeling of pancreatic cancer in orthotopic mouse models." (PMID 39458160, 2024). "Specifically, miRNA-375 targets directly PDK1 and miRNA-200c targets MUC4 (Mucin 4), influencing epithelial–mesenchymal transition and metastatic potential in pancreatic cancer cells." (PMID 39200178, 2024). "The downregulation of miRNA-150 was found to correlate with increased levels of MUC4, an oncoprotein inhibiting pancreatic cancer cell growth." (PMID 39200178, 2024). "This is the first study to implement SPRM to characterize the influence of the human glycocalyx within pancreatic cancer cells on binding interactions of the novel PC vaccine candidate MUC-4." (PMID 38776309, 2024). "MUC4 antibody conjugated with a fluorescent dye was thought to be a good candidate for labeling pancreatic cancer." (PMID 39458160, 2024).
pancreatic cancer (continued). "Mucin 4 (MUC4) belongs to the membrane-bound mucins category and has high expression in pancreatic cancer." (PMID 39458160, 2024). "MUC-4 is predominantly expressed in pancreatic cancer cells, and it has been identified as an ideal vaccine candidate for PC." (PMID 38776309, 2024). "The objective of this work was to investigate the influence of glycans on Mucin-4 (MUC-4) binding interactions in pancreatic cancer (PC) cells, and to determine glycan heterogeneity (as defined here) with Con A and HPA lectins upon removal of N-linked glycans." (PMID 38776309, 2024). "Further studies when detecting CA19-9, MMP7, and MUC4 markers characteristic of pancreatic cancer using SERS at a wavelength of 785 nm showed the great potential of the method for early diagnosis of the disease." (PMID 37232929, 2023). "In a study investigating Gal-3 and its interaction with MUC4 in pancreatic cancer, researchers analysed the serum Gal-3 levels, examined the MUC4–Gal-3 interaction, and assessed its impact on cell adhesion." (PMID 37915694, 2023). "For example, in the ceRNA network, miR-219-1-3p, which occupies the core, negatively regulates MUC4 and has a tumor-suppressive effect in pancreatic cancer." (PMID 36936419, 2023). "MUC4 is a protein of the mucin family that is overexpressed in several pancreatic cancers, and patients with high levels of MUC4 are considered to have poor prognoses." (PMID 37241360, 2023). "In the study of pancreatic cancer, the authors, using the Raman system, detected the MUC4 biomarker at a wavelength of 632.8 nm." (PMID 37232929, 2023). "Cigarette smoke promotes the metastasis of pancreatic cancer by upregulating the expression of MUC4 in pancreatic cancer tissue." (PMID 36674311, 2023). "Previous studies reported that MUC4 played a critical role in tumor progression and metastasis such as breast cancer, ovarian cancer, and pancreatic cancer." (PMID 36091120, 2022). "Various findings indicate that the MUC4 does not only promote the progression of pancreatic cancer functionally, but also is a potential tumor antigen for pancreatic cancer immunotherapy." (PMID 35664731, 2022). "At present, single-marker SERS biosensors have been demonstrated, such as for the detection of serum MUC4 mucin for pancreatic cancer screening in a sandwich assay format." (PMID 35049653, 2022). "A study on pancreatic cancer cells has shown that MUC4 is involved in the resistance to gemcitabine, a common chemotherapy drug used to treat pancreatic cancer." (PMID 35715750, 2022). "Incubation of pancreatic cancer cells with TQ resulted in reduced mucin 4 (MUC4) expression via the proteasomal pathway and stimulated apoptosis through JNK and p38 kinases." (PMID 35236304, 2022). "Mechanistic studies suggest that the presence of MUC4 mediates pancreatic cancer cell invasion and metastasis by stabilizing fibroblast growth factor receptor 1 and oncogenic signaling via interaction with HER3." (PMID 35255004, 2022). "A SERS immunoassay was carried out with these ERLs using a lysate of the pancreatic cancer cell line CFPAC-1 which expresses both MUC4 and CA19-9." (PMID 35049653, 2022). "Large-scale genomic dataset analyses demonstrated that the synergistic effect of MUC4, MUC16, and MUC20 was linked to a statistically significant reduction in OS and elevated HR in colon, stomach, and pancreatic cancers." (PMID 36059804, 2022). "Second, TQ induces pancreatic cancer cells to secrete transforming growth factor-β (TGF-β), which in turn activates the TGF-β pathway and downregulates MUC4, thereby inducing the apoptosis of pancreatic cancer cells." (PMID 36686732, 2022). "Regarding mucins other than MUC1, pancreatic cancer cells become resistant to gemcitabine in parallel with MUC4 expression, and MUC13 overexpression in renal cell carcinoma was reported to play a central role in tumor progression and drug resistance." (PMID 35410995, 2022).